CD177 (CD177 molecule)
Diseases named in the same sentence as CD177 in open-access papers (continued):
Sharing a sentence is not in itself a finding about the gene and the disease.
bacterial infection (20 papers, 2004 to 2025). "CD177 serves as a vital neutrophilic cell gene encoding the glycoprotein of the membrane and the expression of such gene is increased during bacterial infections, burns, and pregnancy." (PMID 37359526, 2023). "CD177 plays an important role in neutrophils recruitment caused by bacterial infection in vivo." (PMID 34489962, 2021). "To examine the influence of bacterial infection on CD177 expression, we downloaded another dataset GSE5772 profiling neutrophil transcripts from normal individuals or septic patients with gram-negative, gram-positive, or mixed bacterial infections." (PMID 25359465, 2015). "The significant upregulation of CD177 in both circulating and airway neutrophils implies an important role for CD177 in neutrophil function in response to bacterial infection in the lung." (PMID 25359465, 2015). "CD177 is a unique marker for neutrophils and is up-regulated upon neutrophil activation during acute inflammatory responses toward stimuli such as bacterial infections." (PMID 23521917, 2013). "Expression of CD177 is also altered during pregnancy and during severe bacterial infections." (PMID 25359465, 2015). "To identify the potential reason why CD177-deficiency resulted in significantly fewer neutrophils in the skin early after bacterial infection, we searched GEO profiles and found that deletion of IKKβ led to a significant increase in CD177 expression from neutrophils." (PMID 25359465, 2015). "All together, we believe that in certain respiratory diseases, especially those that can be exacerbated by secondary bacterial infection and involve neutrophilic inflammation, CD177 could be a potential contribution to the accumulation of neutrophils in the lung airway." (PMID 25359465, 2015). "As CD177 expression on neutrophils is increased in patients with severe bacterial infections, it is potentially possible that under certain inflammatory conditions, CD177-positive neutrophil subsets may support increased neutrophil tissue infiltration as aided by the associated cell surface PR3." (PMID 23226600, 2012). "BacSig was defined as the signature of the host response to bacterial infection using the average expression of five representative genes, including S100A12, CD177, HP, ANXA3, and ARG1." (PMID 38790931, 2024). "Our analysis based on published datasets demonstrated that CD177 expression is increased in circulating and BAL neutrophils when human volunteers were instilled with endotoxin, a condition mimicking bacterial infection." (PMID 25359465, 2015). "The expression of ELANE, MPO and CD177 was not influenced by sex or the presence of bacterial infection." (PMID 34552111, 2021).
infectious disease (7 papers, 2015 to 2024). A disorder directly resulting from the presence and activity of a microbial, viral, or parasitic agent in humans. "The high level of CD177 expression is also maintained in airspace neutrophils, suggesting a potential involvement of CD177 in neutrophil infiltration under infectious diseases." (PMID 25359465, 2015).
respiratory disease (6 papers, 2015 to 2025). "Thus CD177 may provide a target to treat respiratory diseases that are worsened by uncontrolled neutrophilic inflammation." (PMID 25359465, 2015).
breast (2 papers, 2012 to 2024). "CD177 is implicated in transfusion-related acute lung injury, and is also induced in a number of inflammatory settings." (PMID 23118879, 2012).
immune disorders (1 paper, 2025). "The biological functions of CD177 encompass the modulation of human neutrophil migration, the formation of neutrophil extracellular traps (NETs), and the presentation of antigens in various immune disorders." (PMID 41142798, 2025).
CD177 also shares sentences with these, for which no sentence is quoted: glioma (12 papers); diabetes (10); melanoma (10); Alzheimer disease (9); glioblastoma (7); atherosclerosis (5); colon carcinoma (5); HIV-1 infection (5); multiple myeloma (5); cardiovascular disease (4); hepatocellular carcinoma (4); malaria (4); neurodegenerative disease (4); pancreatic cancer (4); type 2 diabetes (4); acute myeloid leukemia (3); anemia (3); Arthritis (3); cervical cancer (3); co-infection (3); essential thrombocythemia (3); Obesity (3); ZIKV infection (3); acute respiratory distress syndrome (2); adenocarcinoma (2); autoimmune disorders (2); B cell lymphoma (2); bladder cancer (2); chronic myeloproliferative diseases (2); Cognitive impairment (2).
A further 127 diseases each share a sentence with CD177 in 2 papers or fewer.